TMEM253 (transmembrane protein 253)
Synonyms: C14orf176; C14orf95; NCRNA00220
Tractability: Antibody: UniProt predicts a signal peptide or a membrane-spanning region.
Gene: Protein-coding gene on chromosome 14 (21,098,811 to 21,103,724, forward strand). Ensembl gene ENSG00000232070.
Subcellular location: Membrane
Gene Ontology:
Cellular component: membrane
Genetic constraint (gnomAD): Loss-of-function variants: 22 observed, 20.9 expected, observed/expected ratio (o/e) 1.05, 90% interval 0.75 to 1.5. The upper end of that interval is the gene's LOEUF score, 1.5, which puts it in group 6 of 6, group 1 being the genes least tolerant of losing a copy. Missense variants: 251 observed, 277.59 expected, observed/expected ratio (o/e) 0.9, 90% interval 0.81 to 1. Synonymous variants: 92 observed, 105.86 expected, observed/expected ratio (o/e) 0.87, 90% interval 0.73 to 1.03.
Homologues: Orthologues: chimpanzee TMEM253 (99% identical), macaque TMEM253 (98% identical), rabbit TMEM253 (79% identical), pig TMEM253 (78% identical), dog TMEM253 (75% identical), mouse Tmem253 (68% identical), rat Tmem253 (68% identical), guinea pig TMEM253 (64% identical).
Diseases named in the same sentence as TMEM253 in open-access papers:
TMEM253 is named in the same sentence as 4 diseases in open-access papers, as found by Europe PMC text mining. Sharing a sentence is not in itself a finding about the gene and the disease.
TMEM253 shares sentences with these, for which no sentence is quoted: Alzheimer disease (1 paper); cognitive decline (1); mild cognitive impairment (1); Parkinson disease (1).